KLK14 (kallikrein related peptidase 14)
Diseases named in the same sentence as KLK14 in open-access papers (continued):
Sharing a sentence is not in itself a finding about the gene and the disease.
colon adenocarcinoma (2 papers, 2018 to 2025). "KLK14 expression also was found on the protein level in 16 gastric cancer cell lines and in human colon adenocarcinomas, while KLK14‐mediated processing of PAR‐2 was identified in the HT29 gastric cancer cell line." (PMID 40621923, 2025).
hepatocellular carcinoma (2 papers, 2017 to 2018). A malignant tumor that arises from hepatocytes. "The apparent lack of KLK14 in the cultural supernatant of hepatocellular carcinoma cells suggested that inhibition of KLK14 is not involved in SPINK6 mediated suppression of tumorigenic phenotypes." (PMID 27999203, 2017).
rosacea (2 papers, 2024 to 2025). A chronic erythematous skin disorder that affects the face. "KLK14 and PAR2 were also discovered to be co-expressed in inflammatory skin disease models, including rosacea and atopic dermatitis." (PMID 39301020, 2024).
allergic disease (1 paper, 2021). An immune response that occurs following re-exposure to an innocuous antigen, and that requires the presence of existing antibodies against that antigen. "Additionally, several proteins, whose expression could be regulated by these variants, had been previously associated with asthma-related traits and/or allergic diseases (e.g., OLFML3, PCSK3, ZNF180, GALNT16, and KLK14)." (PMID 34442380, 2021).
cervical cancer (1 paper, 2025). A primary or metastatic malignant neoplasm involving the cervix. "This study underscores the critical roles of serine proteases KLK5, KLK7, and KLK14 in cervical carcinogenesis, suggesting that these serine proteases are promising targets for the development of novel therapeutic strategies in cervical cancer." (PMID 40753921, 2025). "•Serine proteases KLK5, KLK7, and KLK14 are upregulated in HPV-driven cervical cancer." (PMID 40753921, 2025).
clear cell renal cell carcinoma (1 paper, 2018). "Renal clear cell carcinoma had six KLKs in which increased expression was associated with overall survival (KLK2: HR = 1.69; KLK4: HR = 1.63; KLK8: HR = 1.71; KLK10: HR = 2.12; KLK11: HR = 1.76; and KLK14: HR = 1.86)." (PMID 29707153, 2018).
hypospadias (1 paper, 2020). Hypospadias is the displacement of the urethral meatus on the ventrum of the penis. "This region on chromosome 19 is characterized by clusters of sialic acid-binding Ig-like lectin (SIGLEC) and kallikrein (KLK) genes, among which we identified likely causal relationships with hypospadias (CD33/SIGLEC3, SIGLEC5, SIGLEC7, KLK5, KLK7, KLK10, KLK13, and KLK14)." (PMID 32728162, 2020).
invasive breast carcinoma (1 paper, 2006). A carcinoma that infiltrates the breast parenchyma. "Concordantly with the RNA data, cytoplasmic KLK14 protein expression was significantly higher in invasive breast carcinomas compared to normal breast tissues (P=0.003)." (PMID 16434994, 2006). "KLK14 was shown to be overexpressed in 61% (78 out of 127 cases) of invasive breast carcinomas compared to the adjacent normal breast tissues." (PMID 16434994, 2006).
invasive carcinoma (1 paper, 2006). A carcinoma that is not confined to the epithelium, and has spread to the surrounding stroma. "We observed cytoplasmic KLK14 expression in 99% of intraductal carcinomas and in 96% of invasive carcinomas, respectively, which was significantly stronger than in normal tissue (P=0.003, Fisher's exact test)." (PMID 16434994, 2006). "In 18% (23 out of 127 cases) and 21% (26 out of 127 cases) KLK14 expression was equal and higher in adjacent normal tissue compared to invasive carcinoma, respectively." (PMID 16434994, 2006).
melanoma (1 paper, 2017). A malignant, usually aggressive tumor composed of atypical, neoplastic melanocytes. "Our study showed that only 69% of the analyzed melanoma cell lines ectopically express KLK7, whereas KLK14 and KLK6 are expressed by almost all of the cell lines." (PMID 28636767, 2017).
prostate adenocarcinoma (1 paper, 2020). "Analysis of the prostate adenocarcinoma TCGA dataset indicated that KLK14 mRNA expression was significantly higher in high Gleason score (8 and 9) PCa compared to low Gleason score PCa." (PMID 31630475, 2020).
prostate tumors (1 paper, 2020). "In conclusion, our work showed that KLK14 expression is associated with the development of aggressive PCa suggesting that targeting this protease could offer a novel route to limit the progression of prostate tumors." (PMID 31630475, 2020). "In order to elucidate the molecular functions of KLK14 in the prostate tumor microenvironment, we employed proteomic and transcriptomic pathway analysis, and functional approaches and comprehensively identified the KLK14 substratome, associated downstream pathways, and its cellular functions." (PMID 31630475, 2020). "However, the modulation of KLK14 expression during PCa progression and the molecular and biological functions of this protease in the prostate tumor microenvironment remain unknown." (PMID 31630475, 2020). "However, to date, any variation in the expression levels of KLK14 during PCa progression after neoadjuvant hormonal therapy (NHT) has not been determined, and the molecular mechanisms supporting its protumorigenic effect in the prostate tumor microenvironment remain elusive." (PMID 31630475, 2020). "This indicates that KLK14 expression is reactivated in PCa cells which escape ATT and is increased in metastatic PCa, suggesting that the expression levels of KLK14 in PCa tumors or serum could be informative to predict treatment efficacy or aggressiveness of prostate tumors." (PMID 31630475, 2020).
testicular tumours (1 paper, 2002). "Preliminary studies indicated that KLK14 is differentially expressed in breast, ovarian, prostatic and testicular tumours." (PMID 12439719, 2002).
tumor (15 papers, 2002 to 2025). "With this cutoff value a significant association between KLK14 and tumour grading and positive nodal status was shown, both of which are indicators of a more aggressive course of disease." (PMID 16434994, 2006). "There was a significant association of high KLK14 expression with higher tumour grade (P=0.041) and positive nodal status (P=0.045)." (PMID 16434994, 2006). "When assessing KLK14 expression in terms of predicting survival outcomes, we found an increased risk of relapse and death for patients with KLK14-positive tumours." (PMID 12439719, 2002). "In univariate analysis, patients with KLK14-positive tumours had a significantly increased risk of relapse (decreased DFS) and death (decreased OS) (hazards ratios of 2.31 and 2.21; P=0.001 and 0.005, respectively)." (PMID 12439719, 2002). "Elevated levels of these cytokines have been associated with tumor growth and metastasis, and their regulation by KLK14 may represent a critical link between these processes." (PMID 40621923, 2025). "Bulk RNA-seq analysis from lesions of transgenic mice expressing oncogenes related to HPV infection revealed that Klk5 and Klk7 regulate Klk14 expression, which activates RhoA and NF-κB signaling pathways, thereby promoting tumor progression." (PMID 40753921, 2025). "Our findings add to the understanding of the role of KLK14 in the related processes of wound healing and tumor development." (PMID 40621923, 2025). "Given the potential link to cancer progression, further investigation into KLK14's role in both wound healing and tumor microenvironments is warranted." (PMID 40621923, 2025). "The KLK14 response to DHT and enzalutamide likely proposes a functional component as to the resistance mechanisms of AR inhibitors; additional assays also show that active KLK14 is secreted from both osteoblasts and PCa cells to promote tumor cell migration." (PMID 35129066, 2022). "The novelty of the current study lies in the fact that we tried to modulate the genes KLK2, KLK4, KLK6, and KLK14 to inhibit the progression of PCa via miR-378, which can be produced in tumor cells through EPA, stimulating co-expression of the gene PGC-1β." (PMID 35681793, 2022). "Herein we report a technology platformbased on novel activity-based probes (ABPs) and inhibitors enablingsimultaneous orthogonal analysis of KLK2, KLK3, and KLK14 activityin hormone-responsive PCa cell lines and tumor homogenates." (PMID 34085829, 2021). "To correct for interindividual staining qualities, we normalized the KLK14 immunoreactivity in carcinomas by subtracting the IRS of the normal tissue from the corresponding tumour IRS." (PMID 16434994, 2006). "This KLK14 antibody demonstrated KLK14 protein overexpression in 61% of analysed tumour/normal tissue pairs." (PMID 16434994, 2006). "Cases in which the tumour stained stronger than adjacent normal tissue (IRS>=1) were considered as tumours with high KLK14 expression." (PMID 16434994, 2006). "KLK14 expression significantly impacted survival in subgroups of patients with a tumour size ⩽2 cm and positive nodal, OR and PR status." (PMID 12439719, 2002). "Univariate analysis revealed that KLK14-positive patients with a tumour size ⩽2 cm were about three times more likely to suffer disease progression and four times more likely to die than KLK14-negative patients (P=0.004 and 0.007, respectively)." (PMID 12439719, 2002). "KLK14 also has independent prognostic value in subgroups of patients with a tumour size ⩽2 cm and positive nodal, oestrogen receptor and progestin receptor status." (PMID 12439719, 2002). "The median H-scores of KLK2, KLK4, KLK6, and KLK14 protein expression in the nuclei of normal cells were 9, 24, 12.5, and 14.5, respectively, as compared with the tumor cells (42, 73.5, 43.5, and 62, respectively); therefore, the p values were 0.0027, 0.0009, 0.0062, and 0.0009, respectively." (PMID 35681793, 2022).
tumor (continued). "Our study supports the functional involvement of KLK14 in progression of PCa and suggests that targeting KLK14 could reduce the aggressiveness of PCa cells and limit tumor progression." (PMID 31630475, 2020). "Next, we analysed the KLK14 protein expression data in relation to established prognostic indicators and patient survival and we found a significant correlation of KLK14 protein expression with tumor grade and nodal status." (PMID 16434994, 2006). "Similarly, there was a tendency for an increased risk of disease progression and death in both OR and PR positive patients with KLK14-positive tumours." (PMID 12439719, 2002). "It is therefore exciting to speculate, that the herein described potential of KLK14 to activate membrane-type MMPs may provide a novel mechanism facilitating prostate and breast tumorigenesis, initial cancer cell invasion, and subsequent tumor progression at the sites of metastases formation." (PMID 32575583, 2020). "An optimal cutoff value of 40.5 arbitrary units was selected, to categorise tumours as KLK14-positive or negative." (PMID 12439719, 2002). "This is substantiated by the fact that KLK14, via its serine protease activity, is able to degrade components of the extracellular matrix, including collagen IV α1 chain, collagen XII and matrilin-4 in vitro, which may promote tumour cell invasion and metastasis in vivo." (PMID 16434994, 2006).
cancer (12 papers, 2002 to 2025). A tumor composed of atypical neoplastic, often pleomorphic cells that invade other tissues. "The modulation of IL‐6, IL‐8, and CXCL1 by KLK14 has potential implications beyond wound healing, particularly in cancer." (PMID 40621923, 2025). "Our data show strong evidence that proves that increasing the expression level of miR-378 in cells by EPA induces the PGC-1β gene, which possibly affects KLK2, KLK4, KLK6, and KLK14 gene expression in cancer cells." (PMID 35681793, 2022). "This cell-surface processing sheds more light on the potential of various secreted MMP14 forms to be differentially regulated in normal and cancer cells by extracellular KLK14." (PMID 32575583, 2020). "The involvement of KLK14 in cancer progression has been reported in multiple studies; however, our work is the first to combine multiple omics and functional approaches to decipher the molecular and biological function of this protease." (PMID 31630475, 2020). "It is noteworthy that KLK14 is found in the cytoplasm of nearly all cancers." (PMID 41516101, 2025). "Indeed, KLK14 presence was previously identified as a part of the prostate‐cancer‐related protease network, where secreted KLK14 and KLK4 are recruited to membrane protrusions decorated with cell surface‐bound hepsin and TMPRSS2." (PMID 40621923, 2025). "KLK14-dependent activation of PAR-2, NF-kB, and RhoA signaling suggests a complex interplay between protease signaling, inflammation, and cytoskeletal dynamics in HPV-associated cancers." (PMID 40753921, 2025). "Targeting KLK5, KLK7, and KLK14 may pave the way for novel treatments that prevent cancer progression." (PMID 40753921, 2025). "Augmented expression and release of these molecular messengers in response to the KLK14 treatment tempt us to speculate about the nature of the long‐reported correlation between wound healing and cancer and hint at the need for a precise regulation of the KLK14 expression under normal conditions." (PMID 40621923, 2025). "This demonstrated that EPA could significantly induce PCa cell death by down-regulating the KLK2, KLK4, KLK6, and KLK14 genes in PCa cells, then triggering apoptosis in the cancer cells; however, a similar mechanism did not affect the normal cells." (PMID 35681793, 2022).
infection (1 paper, 2020). The state of being infected such as from the introduction of a foreign agent such as serum, vaccine, antigenic substance or organism. "Pathway analysis performed using ingenuity pathway analysis (IPA) on KLK14‐modulated proteins indicated an activation of cellular functions related to cell motility and proliferation and an inhibition of cellular functions related to cell death or infection." (PMID 31630475, 2020).
KLK14 also shares sentences with these, for which no sentence is quoted: alopecia (1 paper); amyloid (1); Arthritis (1); asthenospermia (1); asthma (1); gastric cancer (1); lymph node metastasis (1); male infertility (1); metabolic disorders (1); metastatic disease (1); neurodegenerative disease (1); Obesity (1); pancreatic cancer (1); papillary renal cell carcinoma (1); prostate (1); skin disorder (1); testicular cancer (1); urothelial bladder carcinoma (1).